IL2 (interleukin 2)
Diseases named in the same sentence as IL2 in open-access papers (continued):
Sharing a sentence is not in itself a finding about the gene and the disease.
depression (continued). "Further to this, it has also been shown that cytokine immunotherapy in the form of IL-2 and IFN-α for the treatment of hepatitis C (Hep C) and certain types of cancer, such as malignant melanoma, can induce depression in 30% to 50% of these patients who are otherwise psychiatrically normal." (PMID 26775294, 2016). "Interleukin-2 (IL-2) and interleukin 6 (IL-6) are two commonly used markers of inflammation, and increased expression of both IL-2 and IL-6 has been shown in cardiovascular disease, COPD, loneliness and depression." (PMID 29082106, 2016). "These plausible relationships between IL-2, IFN-γ, and glucocorticoid signaling calls for further research that could provide mechanistic insight into the link between chronic inflammation, depression, and its comorbidity." (PMID 26403459, 2016). "Furthermore, patients with painful neuropathy have increased serum expression of TNF and IL-2 (a T cell activator), with the highest levels of TNF found in patients with comorbid depression." (PMID 25986444, 2015). "Our results suggest that the proinflammatory cytokines (IL-2, IL-12, and TNF-α) and MCP-1 were significantly higher, whereas anti-inflammatory cytokines IL-4 and TGF-β1 were significantly lower in patients with major depression than those of healthy controls." (PMID 18317531, 2007). "Their conclusion was that depression does not necessarily influence the serum levels of IL-2 and IL-6, but it is possibly related to BMS." (PMID 16864905, 2006). "For example, TNF, TLR4, IL-2, BCL-2, etc., are closely related to inflammation, and these targets may be the key targets of Hyp, the main active component of HP, in the treatment of depression." (PMID 36556951, 2022). "In particular, tumor necrosis factor alpha (TNFα), interleukin-2 (IL-2), interleukin-6 (IL-6), interleukin-13 (IL-13), interleukin-18 (IL-18), C-reactive protein (CRP), chemokine-2 (CCL2), and chemokine-11 (CCL11) are elevated in depression based on multiple meta-analyses." (PMID 32351416, 2020). "In particular, pro-inflammatory cytokines like interleukin-2 (IL-2), IL-6, soluble IL-6 receptor, tumor necrosis factor-α (TNF-α) and interferon-γ (IFN-γ) are increased while anti-inflammatory cytokines like IL-4 and IL-10 are decreased during depressive disorders." (PMID 33066277, 2020). "However, in TNM stage 0 or I non-acral melanoma, depression was negatively correlated with IL-12 (P = 0.018, Rho = −0.534) concentrations, and low QOL negatively with IL-12 (P = 0.043, Rho = −0.468) and IL-2 (P = 0.023, Rho = −0.519)." (PMID 36405903, 2022).
asthma (133 papers, 2009 to 2026). "Asthma was associated with the increased expression of pro-inflammatory cytokines, including IL-2, IL-5, IL-13, IL-17A, IL-22, IL-33, and TNF-α, and reduced levels of anti-inflammatory cytokine, IL-10 and adipokine, leptin in the circulation." (PMID 39902293, 2024). "With regard to asthma, the inflammatory mechanisms linked to leptin and interleukin-2 (IL-2)—which contribute to the high incidence and severity of the disease in children—are also implicated in the severity of COVID-19 infection." (PMID 39457167, 2024). "Hypermethylation of IL-2 gene site 1 was observed in newborns of mothers with atopic asthma, while increased methylation indicated an increased risk for asthma exacerbations." (PMID 37927185, 2023). "Increased IL-2 was shown to be associated with an increased risk of asthma in children, while animal models showed that IL-2 also affected other tissues, such as during cardiovascular recovery." (PMID 37927185, 2023). "Although methylation of the IL-2 gene site 1 has been associated with asthma risk in newborns, studies investigating DNA methylation disturbances in PN are still limited, while epigenetic biomarkers are not even considered in clinical diagnostics." (PMID 37927185, 2023). "Th2-type cytokines such as IL-4, when increased relative to Th1 cytokines (IFN-γ, IL-2), cause asthma and exercise-induced allergy and induce disease vulnerability." (PMID 32731626, 2020). "Where asthma and the common cold are directly linked to Interferon-gamma (IFNg), IL-8, IL-2 and IL-5, diarrhea is linked to IL-18." (PMID 32746922, 2020). "Of note, both IL-2 and interferon pathways play an important role in cell-mediated immunity and have previously been implicated in asthma pathogenesis." (PMID 26691723, 2015). "IL-2 is a pro-inflammatory cytokine involved in the development of Treg cells and associated with eosinophil proliferation, airway inflammation and hyperreactivity, and impaired lung function in asthma patients." (PMID 37784136, 2023). "Moreover, epigenetic loci modified by albuterol were located in genes enriched in asthma-associated processes (i.e., TNF-α, NF-kB, and IL-2 signaling pathways) and likely regulated by a potential asthma drug (i.e., TSA)." (PMID 37784136, 2023). "In addition to corroborating a mechanism of genetic risk previously proposed in asthma, the finding is intriguing given the recently characterized function of the gene product in suppressing IL-2 production by these cells." (PMID 31945409, 2020). "The aim of this study was to assess whether ex vivo production of interleukin 2 (IL‐2), a T‐cell survival factor, associated with clinical features of asthma severity, the proportion of blood Th2 cells and Th2 cell responses to GC." (PMID 30994266, 2019). "The most important characteristic feature of asthma is chronic airway inflammation which is associated with increased number of Th2lymphocytes and their cytokines (IL-4, IL-5, IL-9, and IL-13) while Th1 lymphocytes and their cytokines (IL-2, IFN-γ, and IL-12) are reduced." (PMID 28824424, 2017). "Finally, GO analysis of differentially methylated loci associated with a persistent-asthma phenotype revealed an enrichment of immune-related pathways including IL-2 and interferon type I signalling pathways which have previously been implicated in asthma pathogenesis." (PMID 26691723, 2015). "In the pediatric cohort, children with non-T2 asthma displayed a prominent non-T2 inflammatory signature, with significantly higher serum IL-2, IFN-γ, IL-6, and IL-17A compared with T2-high children (p < 0.05 for all indicated comparisons)." (PMID 41601686, 2026). "Elevated IL-4, IL-9, and TNF-α were observed in non-T2 asthma compared with T2-high asthma, while children exhibited higher levels of IL-2, IL-6, IFN-γ, and IL-17A than adults." (PMID 41601686, 2026).
asthma (continued). "Purpose of this study is to investigate dynamics of CRP, serum cytokines (IL-2, IL-6, IL-10, IL-17) in patients with asthma and COPD, as well as to perform a correlation analysis with the clinical manifestations of the diseases within a year after vaccination." (PMID 39937802, 2025). "Next, the levels of IL-2 and IL-22 showed a significant increase only in asthma groups (NW-A and OO-A) compared to the NW group." (PMID 39902293, 2024). "The children with asthma had an inflammatory profile that was characterized by increased levels of several pro-inflammatory cytokines, including IL-2, IL-5, IL-13, IL-17A, IL-22, IL-33, TNF-α, and reduced level of anti-inflammatory cytokine, IL-10." (PMID 39902293, 2024). "Immune and inflammatory pathways (eg, IL-2, TNF-α, NF-κB, and C/EBPs) underlie microbiome-epigenetic associations with asthma treatment, representing potential therapeutic pathways to be targeted." (PMID 38906272, 2024). "Asthma inflammation is well immunomodulated by thymoquinone extract, which inhibits IL-2, IL-6, and PGE2 in T cells and IL-6 AND PGE2 in monocytes." (PMID 36684115, 2023). "These and other asthma risk variants at 17q21 (rs4065275, rs12936231, rs7216389) increase ORMDL3 expression on CD4+ T cells, reducing interleukin-2 production." (PMID 37762787, 2023). "Elevations in sCD40L have been associated with pulmonary arterial hypertension (PAH), while IL-2 can induce pulmonary microvasculature injury and generate an asthma-like bronchoconstriction." (PMID 36844201, 2023). "Affected genes were enriched in asthma-relevant processes, including IL-2, TNF-α, and NF-κB signaling pathways, and were more likely to be regulated by Trichostatin A than chance." (PMID 37784136, 2023). "Non‐T2 cytokines, such as IL‐2, IL‐10, and IFN‐γ, have been implicated in the pathogenesis of asthma, particularly in patients with severe disease." (PMID 35344278, 2022). "The observed reductions in IL-2 and IL-12 in the serum by ~ 40–60% compared to normal mice confirm that asthma was induced by OVA." (PMID 36115955, 2022). "To determine the relationship between PRB1 and type 2‐high asthma further, we detected the levels of IL‐2, IL‐4, IL‐5, IL‐6, IL‐10, IL‐13, IL‐17, and INF‐γ in the induced sputum supernatant." (PMID 35344278, 2022). "In ConA-stimulated splenocyte supernatant, all P. cocos extract doses exhibited a significant increase in IL-2 level, compared to that in the asthma group." (PMID 33919400, 2021). "The cytokines (IL-4, 5, 6, 10, and 13) produced by Th2 cells have been shown to play pivotal roles in the development of eosinophilic inflammation in asthma, while interleukin-2 and interferon-γ were produced by Th1 cells." (PMID 33859559, 2021). "The loss of IL-2 was shown to decrease ILC2 function, thereby reducing the lung inflammation caused by asthma in IL-2-deficient mice." (PMID 34177881, 2021). "Glucocorticoids are old anti-inflammatory drugs that have been shown to be very effective in treating asthma and can quickly inhibit the transcription of pro-inflammatory cytokines such as IL-2, IL-3, IL-4, IL-5, and IL-623." (PMID 32760206, 2020). "Interleukin-2 (IL-2) and interleukin-4 (IL-4) are overexpressed in the airways of patients with corticosteroid-resistant asthma." (PMID 32112175, 2020). "Cytokines such as IL-2, IL-12p40, and IL-13 increased in the present study and reduced by the hybrid are documented to be important mediators of asthma." (PMID 31779093, 2019). "Here, we measured IL‐2 production from peripheral blood cells and assessed its relationship with clinical features of asthma, type 2 inflammation and the effect of this cytokine on GC responses of human Th2 cells." (PMID 30994266, 2019). "Direct in vitro evidence points to the release of some asthma-related cytokines and a prostanoid with inflammatory properties (IL-2, IL-6, PGE2) from human immune cells (including T-lymphocytes and monocytes)." (PMID 30333747, 2018).
asthma (continued). "For instance, interleukin-2 (IL-2) was found to be increased in the broncho-alveolar lavage fluid (BALF) of patients with asthma." (PMID 30333747, 2018). "IFN-gamma and IL-2 are produced by Th-1 cells which act as a protective mechanism in asthma and their levels were lowered in OVA sensitized mice." (PMID 28293189, 2017). "IL-2 is a Th1 cytokine, and inhalation of IL-2 induces asthma-like symptoms in humans and aggravates airway inflammation in a mouse model of asthma." (PMID 29234369, 2017). "BALB/c asthma model mice were administrated 5,000 IU of IL-2(PEG) plus 1 μg of budesonide or saline intratracheally for 3 days." (PMID 27527926, 2016). "When the asthma model mice were challenged with antigen for the second time, the immune response was relatively weaker, making it possible to take combined use of IL-2 and glucocorticoid as a long-term and convenient methodology for asthma." (PMID 27527926, 2016). "Using a fixed 2-μg dose of budesonide per asthma model mouse, we were able to show that a corresponding dose of 10,000 IU IL-2(PEG) per mouse was optimal for Treg cell upregulation." (PMID 27527926, 2016). "We have revealed for the first time that PTP-RR is also expressed in PBMCs and the U937 human monocytic cell line, and shows reduced expression in severe asthma and IL-2/IL-4-induced corticosteroid insensitivity, respectively." (PMID 27013170, 2016). "Compared with treatment with IL-2(PEG) or budesonide alone, intratracheal treatment with a combination of 5,000 IU IL-2(PEG):1 μg budesonide markedly reduced AHR of asthma model mice." (PMID 27527926, 2016). "We demonstrated that knocking-down PTP-RR reduces GR nuclear translocation with concomitant induction of corticosteroid insensitivity, and that PTP-RR expression was reduced in severe asthma and in the IL-2/IL-4-induced corticosteroid insensitive model." (PMID 27013170, 2016). "In this study, we show that local application of glucocorticoid and IL-2 via the airway can effectively upregulate Treg cells and alleviate the pathological process of asthma in mice model." (PMID 27527926, 2016). "CD4+ T cells showed the greatest increase (threefold) in ORMDL3 expression in individuals carrying the asthma-risk alleles, where ORMDL3 negatively regulated interleukin-2 production." (PMID 27848966, 2016). "With regard to asthma and allergy, IL-2 appears to exert harmful effects as IL-2 induced STAT5 phosphorylation drives TH2 differentiation." (PMID 26459392, 2015). "One patients (pt 5) dropped-out from the study for an asthma attack after the first dose of IL2 requiring interruption of treatment." (PMID 26413873, 2015). "Studies in other models (asthma, trauma) demonstrated that Th1 cytokines such as IL-2 and IFN-gamma were increased whereas Th2 cytokines such as IL-4, IL-10 and IL-13 were suppressed." (PMID 24732949, 2014). "Th2 cells, which are characterized by IL-4, IL-5, IL-9 and IL-13 cytokine production, predominate in asthma, whereas Th1 cells producing IFN-γ, IL-2 and TNF have rarely been associated with asthma." (PMID 25132806, 2014). "In mild asthma, Tbet expression was significantly correlated with Il2, Il4, Il5, Il6, Il13, and Tnfα expression." (PMID 23781124, 2013). "In severe asthma, the largest change (110-fold) is observed in Ifnγ expression followed by Il13, Il2, Il4, Il10, Il6, Il5, and Tnfα, respectively." (PMID 23781124, 2013). "Earlier studies have demonstrated that treatment with IL-2/IL-4 can mimic the corticosteroid insensitivity seen in severe asthma." (PMID 22911818, 2012). "Fully in line with this finding, we here show that sitostanol induced a Th1 response in PBMCs from asthma patients, indicated by an increase in the concentration of cytokines IL-2 and IFNγ." (PMID 23091602, 2012). "Basal IL-2 level in PBMCs from patients with severe asthma (median (range): 5.6 (0.0;19.0) pg/ml, n = 10; p<0.05) was significantly higher compared to those of healthy volunteers (0.0 (0.0;2.6) pg/ml, n = 10)." (PMID 22911818, 2012).
asthma (continued). "PP2A protein expression was reduced in PBMCs from severe asthma and IL-2/IL-4 treated U937 cells, and also very interestingly, immunoprecipitated PP2A activity corrected by protein expression was also decreased in both samples." (PMID 22205926, 2011). "We found that phosphorylation levels of PP2AC-Tyr307 were significantly increased in PBMCs from severe asthma and IL-2/IL-4 treated U937 cells." (PMID 22205926, 2011). "In patients with GC-R asthma, a combination of increases in both IL-2 and IL-4 reportedly reduced GR binding affinity in PBMC, and these effects were reversible and blocked by interferon (IFN)-γ." (PMID 23675190, 2010). "Our data demonstrating enhanced accumulation of not only IL-13+ but also IFN-γ+ T cells from asthmatic subjects in response to IL-2 suggest the importance of antigen-independent stimulation of T cells in asthma." (PMID 20667106, 2010). "Bronchial biopsy specimens from patients with GC-R asthma revealed over-expressions of IL-2, IL-4 and IL-13 and a reduction in the GR affinity of inflammatory cells." (PMID 23675190, 2010). "There was a significant interaction between asthma and gender for IL-2-stimulated accumulation of IL-13+ T cells (p = 0.003) but not IFN-γ+ T cells (p = 0.42)." (PMID 20667106, 2010). "Our cytokine analysis revealed that pediatric non-T2 asthma is characterized by elevated Th1 and Th17 cytokines, including IL-2, IL-6, IFN-γ, and IL-17A, accompanied by the downregulation of immunoglobulin-associated genes, indicating an attenuated Th2 signature and reduced atopy." (PMID 41601686, 2026). "In the pediatric cohort, non-T2 asthma was characterized by higher circulating IL-2, IFN-γ, IL-6, and IL-17A compared with T2-high disease, whereas these same Th1/Th17-associated and pro-inflammatory cytokines were uniformly low and non-discriminatory in adults." (PMID 41601686, 2026). "When we tested for nutrients associated with proinflammatory cytokines, FAs showed the most prominent negative associations with IL-2, IL-10, IL-13, and IL-17A, which play key roles in the inflammatory processes underlying asthma." (PMID 41256924, 2025). "In mice with ova-induced bronchial asthma, the administration of EGCG via tail vein injection demonstrates a notable amelioration of asthma symptoms, along with a reduction in lung infiltration of inflammatory cells and levels of inflammatory factors IL-2, IL-6, and TNF-α." (PMID 39411430, 2024). "Furthermore, the cytokines regulated by NF‐κB, including IL‐1β, IL‐2, ICAM‐1, and VCAM‐1 are associated with obese asthma." (PMID 38286741, 2024). "Gene-set enrichment analyses revealed that epigenomic modifications of albuterol could participate in asthma-relevant processes (e.g., IL-2, TNF-α, and NF-κB signaling pathways)." (PMID 37784136, 2023). "In addition, EGR3 was reported to be overexpressed in the lung of asthma patients and regulates the expression of IL-2, IL-6, and IL-8." (PMID 36979655, 2023). "Indeed, both the cytokines IL-4 and IL-5 as well as IL-13 were augmented in asthma mice, while the level of anti-inflammatory cytokines IL-2, IFN-ɣ, and IL-10 were drastically reduced." (PMID 36685604, 2022). "In addition, the study showed that the expression of MUC5AC was also reduced after treatment with dexamethasone in asthma patients, and dexamethasone can also inhibit the expression of IL-2 and IFN-γ." (PMID 35578178, 2022). "Additional cord blood studies show that the association of increased methylation of a functional CpG site in the IL-2 promoter increased the likelihood of severe asthma exacerbations, as well as hospital admissions for asthma/wheeze in children between 2 and 8 years of age." (PMID 35693821, 2022). "Further, among males with asthma, lower levels of TH1 cytokines were statistically significantly associated with higher levels of PFDA (IL-2 only), and higher levels of TH2 cytokines were statistically significantly associated with higher levels of PFOA (IL-4 and IL-5) and PFBS (IL-5 only)." (PMID 34712855, 2021).